IL7 (interleukin 7)
Diseases named in the same sentence as IL7 in open-access papers (continued):
Sharing a sentence is not in itself a finding about the gene and the disease.
tumor (continued). "Mice receiving the combination of CAR T cells+dex+IL-7, but not the CAR+IL-7 group, had circulating human T cells on day 25, which corresponded with a significantly lower tumor burden over time." (PMID 38140726, 2024). "While the injected CAR-T cells showed a significant effect, which was dependent on IL-7 and CCL19 secretion, the depletion of host T-cells abrogated the anti-tumor effects, suggesting co-operation between adoptively transferred and native T-cells in facilitating tumor rejection." (PMID 38339310, 2024). "However, the addition of IL-7 and IFN-α mRNA augmented the anti-tumor activity of IL-12 mRNA in the huHSC-NCG-hIL15 mouse model." (PMID 39290693, 2024). "When exposed to IL-7, CAR-T cells persist and enhance anti-tumor activity in vivo." (PMID 39093440, 2024). "C5/IL7-CAR-T cells exhibited significantly greater proliferation rates than did the other CAR-T cells, suggesting that C5/IL7-CAR-T cells more rapidly expanded in response to tumor cells." (PMID 39450160, 2024). "A study was conducted to genetically engineer TCR-T cells (7 × 19 P1A T) to express both IL-7 and CCL19, which resulted in complete tumour regression and prolonged survival in half of the mice after 7 × 19 P1A T treatment in a murine mast cell tumour P815 model." (PMID 38675377, 2024). "Our data demonstrate that following adoptive transfer, TCR-engineered TSCM-like cells generated in culture with IL-7/IL-15 maintain a reservoir in the tdLNs accounting for nearly a quarter of all CD90.1+ cells, whereas tumor-infiltrating cells express a differentiated effector memory phenotype." (PMID 37400675, 2023). "The research and development situation of IL-7 as the next-generation anti-tumor drugs in recent years is not optimistic." (PMID 36936961, 2023). "We transduced SNAP-synNotch Jurkat cells with this response vector and co-incubated them with several different antibodies and antigen positive and negative tumor cells for evaluation of IL-7 response gene expression by ELISA." (PMID 37160880, 2023). "C7R activates the IL-7 signaling axis without needing extracellular cytokines and enhances the anti-tumor activity of anti-AXL CAR T-cells in TNBC models." (PMID 38201551, 2023). "For instance, the transduction of CAR-T cells to express IL-7 and the chemokine CCL-19 not only enhances T cell survival, infiltration and accumulation within tumours but also culminates in the complete regression of established solid tumours and extended survival in murine models (Ref." (PMID 38095091, 2023). "Contrasting this result with the level of circulating IFN-γ indicates that addition of IL-7–CBD boosts only tumor-specific inflammation but not systemic inflammation." (PMID 38019919, 2023). "Of other cytokines, tumour necrosis percentage positively correlated with IL7 in Cohort 2B but not in 2 A (beta = 0.190 and 0.083, P = 0.017 and 0.375, respectively), and with IL6 in Cohort 2A (beta = 0.191, P = 0.043)." (PMID 37031328, 2023). "For example, transduction of CAR-T cells to express IL-7 and the chemokine CCL-19, not only enhanced T cell survival, infiltration and accumulation in the tumor, but also achieved complete regression of pre-established solid tumors and prolonged mouse survival." (PMID 35432319, 2022). "Thus, we generated CAR-T cells armored with IL-7 to prolong the persistence of infused T-cells, particularly CD4 + T cells, and enhanced anti-tumor response." (PMID 35869100, 2022). "And they demonstrated that IL-7 and IL-12 combination virotherapy could increase the intratumoral CD8+ T cells clonality and anti-tumor response rate as well." (PMID 35459242, 2022). "In another strategy, IL-7-loaded oncolytic adenoviruses (oAD-IL7) were used in vivo to improve the effectiveness of B7H3-CAR-T cell therapy by enhancing T cell persistence, which led to prolonged survival of the GBM tumor-bearing mice." (PMID 36140275, 2022).
tumor (continued). "Culturing antitumor T cells or CAR-T cells in IL-7 or IL-15 rather than IL-2 alone has been demonstrated to produce cells with greater in vivo tumor control and greater preservation of Tscm phenotype." (PMID 36741362, 2022). "For example, IL-7-loaded oncolytic adenovirus (oAD-IL7) combined with B7-H3 CAR T cells for the preclinical GBMs mice model is under investigation and has shown synergic survival benefit with tumor regression." (PMID 35265074, 2022). "Favorable, anti-inflammatory cytokines, such as IL-1RA, IL-7, and MIP-1β were detected in higher concentrations in responding patients, while pro-inflammatory, tumor-promoting cytokines, such as IL-18 and IL-1β, were higher in patients with early progressive disease." (PMID 36091056, 2022). "Compared to those of tumor-bearing mice, the expression levels of stimulatory molecules, including CXCL10, IL-12, and IL-15, were significantly upregulated, while the expression level of IL-7 was downregulated." (PMID 36389684, 2022). "This suggests that IL-7 could enforce more Th1-prone signature compared to 28z CAR-T group, which could translate to efficient tumor control." (PMID 35869100, 2022). "Moreover, co-administration of IL-7 with tumor-reactive CD4+ T cells in a mouse model promotes their expansion, persistence and antitumor activity, corroborating the potential use of IL-7 as an adjuvant for CD4+ T cell-based ACT." (PMID 35008422, 2022). "Second, we notably do not see increased tumor control with an autocrine circuit that produces the homeostatic cytokine IL-7." (PMID 36520915, 2022). "The murine Il-7 (mIl-7) gene has also been inserted into the genome of the nonlytic Newcastle disease virus (NDV) LX strain, which is an autologous tumor vaccine modified using the reverse genetic method that has been used against murine tumors (HCC, lymphoma, and melanoma)." (PMID 34956167, 2021). "As ACT using T cells essentially requires prior lymphodepletion, we first examined the anti-tumor effects of the Fc fusion protein of IL-7 (IL7-Fc) under none, mild, and severe lymphopenic conditions." (PMID 34440787, 2021). "In order to minimize systemic toxicity and induce the accumulation of high cytokine concentrations at the tumour site, CAR‐T cells were modified to produce IL‐12, IL‐18, IL‐7, IL‐15 and IL‐21 cytokines, and activation and persistence of CAR‐T cells were, therefore, enhanced in vivo." (PMID 34585512, 2021). "Furthermore, IL‐6, IL‐7, IL‐8, and TGF‐β1 Abs (10 μg/mouse twice times per week, i.v.)markedly inhibited activated CAFs‐induced KYSE30 tumor malignancy in vivo." (PMID 34459125, 2021). "Previous studies indicate that systemic treatment of IL7-Fc induces proliferation of CD8+ T cells and improves anti-tumor responses by increasing CD8+ T cells in the periphery and by promoting the accumulation of CD8+ T cells in tumor tissues." (PMID 34440787, 2021). "Tumor-bearing mice received CTX, activated pmel-1 Thy1.1+CD8+ T cells, and IL-2 and/or IL7-Fc." (PMID 34440787, 2021). "Although IL-7/IL-15-treated polyclonal T cells have less differentiation and more anti-tumor efficiency, they either show no significant T cell expansion advantage or a small T cell and CAR T cell expansion compared to IL-2 only-treated cells." (PMID 34217218, 2021). "The addition of IL-12, but not IL-7 or IL-15, to the cells improved tumor growth inhibition and extended survival compared with mRBC-OVA-4-1BBL and the PBS control, resulting in 4/8 cures." (PMID 33976146, 2021). "MSCs engineered to release IL7 and IL12 shift the chronic inflammatory Th2 profile of the tumor microenvironment into a more favorite Th17/Th1 profile with an improved and prolonged anti-tumor CAR T cell response." (PMID 32260097, 2020). "We found that NKG2DIL7-CAR T cells produced a relatively greater amount of IL-7 compared with conventional CAR T cells in the absence of a tumor." (PMID 32698361, 2020).
tumor (continued). "The results revealed a higher proportion of Tcm-phenotypic cells in the tumor tissue from the mice treated with NKG2DIL7-CAR T cells, suggesting that IL-7 might be beneficial to the formation of central memory T cells." (PMID 32698361, 2020). "Testing combinations of various cytokines in T cell culture media revealed that tumor antigen specific CD4+ T cell growth was improved by culturing in IL-1β, IL-2, IL-6, IL-7, IL-15, IL-21, IL-23, and TGFβ, and that the addition of TGFβ was critical for the improved performance of the cocktail." (PMID 33362774, 2020). "In the tumor stage, IL-7 gradually decreased in the subgroup but there was no statistical difference." (PMID 32381120, 2020). "We co-injected NSG mice with anti-CEA CAR T cells, IL7/IL12 modified MSCs, and CEA+ tumor cells." (PMID 32260097, 2020). "The same IL7/IL12 MSCs enhanced the allogeneic response of T cells independently of the CAR implying that IL7/IL12 engineered MSCs booster the specific T cell response and initiate antigen-independent anti-tumor activities." (PMID 32260097, 2020). "MSCs engineered to release IL7 and IL12 as “of-the-shelf cell therapy additives” will help to establish a pro-inflammatory response that prolongs the T cell anti-tumor attack and successfully counteracts repression through the tumor environment." (PMID 32260097, 2020). "Overexpression of IL-7 in tumor tissue did not significantly differ with respect to the extent of the primary tumor." (PMID 31185636, 2019). "Taken together, these findings demonstrated that IL-7 does not augment tumorigenesis or tumor growth, despite promoting invasion and migration of PC-3 cells." (PMID 31061414, 2019). "Our study investigated the anti‐tumour role of IL‐7 in tumour cells itself and not the immune responses." (PMID 31599032, 2019). "Although the function of IL-7 in cancer has not reached the consistence, mounting evidence in vivo showed that the administration of rhIL-7 is beneficial for the tumor treatment via promoting the development of activation T cells, B cells and NK cells." (PMID 31138762, 2019). "As a member of the IL-2 cytokine family and a distant paralog of IL-7, oncogene properties of TSLP, such as pro-tumorigenic, cancer cell protective, and tumor growth promoting properties, have been reported in various animal models of cancers, as well as in studies conducted on humans." (PMID 31023965, 2019). "However, another study that engineered “armored” mesothelin CAR T cells that constitutively expressed both the cytokine IL-7 and the chemokine CCL19 showed complete tumor regression and prolonged survival in a solid tumor mouse model." (PMID 30804938, 2019). "Additionally, IL-15 is able to reverse tumor-tolerant CD8+ T cells, when IL-2 and IL-7 were unable to, restoring antigen responsiveness and leading to tumor clearance." (PMID 30842774, 2019). "In preclinical tumor models, IL-7 alone does not allow the development of anti-tumor immune response yet amplifies a response induced by vaccination or adoptive T cell transfer." (PMID 30922400, 2019). "Moreover, CXCR3 levels expressed on CD8+ T cells isolated from tumor-free WT and ADAM28 KO mice and stimulated ex-vivo with IL-2 and IL-7 were similar between both groups." (PMID 30647853, 2018). "Splenic IL-8 was associated with weight and muscle loss and had a negative association with the same tumor proteins associated with increased TFBW (IL-4, Flt-3L, IFNγ, IL-7) and skeletal muscle weights (Flt-3L, IFNγ)." (PMID 30513792, 2018). "Lymphocytes expanded in IL-7/15/21 were then found to be as effective as lymphocytes cultured in other cytokines at impeding tumor growth or curing tumors in vivo without vaccine or exogenous cytokine administration." (PMID 28146052, 2017). "However, CTX chemotherapy creates an environment that drives robust effector differentiation of adoptively transferred tumor-specific CD4+ T cells, giving rise to polyfunctional CD4 effector cells capable of responding to exogenous IL-7." (PMID 28939858, 2017).
tumor (continued). "Step 2 exposure to exogenous IL-7 or IL-7+IL-2 produced selective and sustained expansion of both CD4+ and CD8+ peptide-specific T-cells with a predominant interferon-?-producing T1-type, as well as the antigen-specific ability to lyse tumor targets." (PMID 27974697, 2017). "Using regulatory T (Treg)-cell-enriched mouse tumor model, we determine that M6PRhigh IL-2 effectors but not M6PRlow IL-7 effectors adoptively transferred into tumors are vulnerable to Treg Gzm-B-mediated cell apoptosis." (PMID 28496990, 2017). "We demonstrate that tumor-resident Treg cells preferentially eliminate M6PRhigh IL-2 effectors rather than M6PRlow IL-7-effectors through Treg Gzm-B-mediated cell apoptosis." (PMID 28496990, 2017). "Despite of a paucity of IL-7 in the immune milieu, CTX preconditioning allowed adoptively transferred naïve tumor-specific CD4+ T cells to undergo effector differentiation and regain IL-7Rα expression, giving rise to IL-7-responsive polyfunctional CD4+ effector cells." (PMID 28939858, 2017). "IL-7(CD45.1) effectors cultured with or without TWS119 were then directly injected into tumors of tumor-bearing B6 (CD45.2) mice together with Gzm-B substrate GranToxiLux." (PMID 28496990, 2017). "Importantly, IL-7 restored functionality in CD8+ T cells during chronic viral infections and in tumor models." (PMID 28356069, 2017). "Nevertheless, steady-state IL-7 production is not sufficient for effective anti-tumor T cell responses under non-lymphopenic conditions." (PMID 27447484, 2016). "Our team recently found that IL-7 produced in the spleen of tumor-bearing mice was significantly decreased (data not published)." (PMID 25955647, 2015). "Here we could see a clear IL-7-dependent survival effect of the derived Zeb2-overexpressing mouse T-ALL cell lines in vitro and an effect on their ability to initiate secondary tumours after transplantation." (PMID 25565005, 2015). "The simultaneous intraperitoneal administration of PAP-GMCSF, -IL2, -IL4 and -IL7 significantly prevented tumor induction and inhibited the tumor growth in the PAP-expressing tumors, yet not in the PSA-expressing tumors." (PMID 25632844, 2015). "Our data suggest that OXP plus IL-7 treatment inhibits tumor cell growth by immunoregulation rather than direct cytotoxicity." (PMID 24465710, 2014). "IL-7 also enhances the expression and secretion of IL-3 and GM-CSF in activated human T-cells and downregulates TGF-beta in macro-phages, thereby accelerating anti-tumor immune responses." (PMID 24551818, 2014). "Our data suggest that OXP plus IL-7 treatment inhibits tumor cell growth by immunoregulation rather than directly cytotoxicity." (PMID 24465710, 2014). "Five mouse-specific cytokines were significantly (P=0.03) higher expressed in VEGFA165 tumours compared with control tumours: interleukin 5 (IL5), IL7, chemokine (C-X-C motif) ligand 9 (CXCL9, MIG), colony-stimulating factor 1 (macrophage) (MCSF) and interferonγ (IFNG)." (PMID 22045186, 2011). "Tumor and bone vitality and IL-7 expression were assessed in implanted bone, affected or not by A549." (PMID 20067635, 2010). "The IL-7 expression by tumor mass (in mice with contralateral bone) and by bone stromal cells did not lead to high serum IL-7 levels." (PMID 20067635, 2010). "T cells rescued by IL-2, IL-15 and IL-21 killed peptide coated target cells and tumor cells more efficiently than T cells cultured with IL-7 or without cytokine supplementation." (PMID 17406677, 2007). "Similarly, CD4+ T cells cultured in the presence of IL-7 plus IL-23 had 11% IFN-γ positive cells in response to MCA205 tumor with minimal spontaneous production and minimal response to MCA207 tumor digest." (PMID 15566571, 2004). "Clinical studies have demonstrated that IL-7 plays a pivotal role in enhancing the proliferation, survival, and functional competence of both CD4+ helper T cells and CD8+ cytotoxic T lymphocytes—key effector subsets that orchestrate adaptive anti-tumor immune responses." (PMID 41450878, 2025).
tumor (continued). "Interestingly, IL-7 expression alone did not promote the clonality of tumor-infiltrating CD8+ T cells." (PMID 40957993, 2025). "This suggests that IL-7 does not originate from tumor cells or their microenvironment." (PMID 41360767, 2025). "Therefore, the significant difference in T cell proliferation observed in the ex vivo study, by manipulating the CM of the CTSS-knockdown tumor with or without the IL-7 recombinant protein, pursued the interaction that occurred in the local tissue." (PMID 40707961, 2025). "Furthermore, the B16-LX/IL-7 vaccine induced a tumor-specific IFN-γ response, as splenocytes or TILs from B16-LX/IL-7-treated mice failed to produce IFN-γ when stimulated with EL-4 tumor cell lysate." (PMID 40957993, 2025). "Moreover, although LTA + IL-7 vaccines improved systemic expansion of LTA-specific CD8+ T cells with memory phenotypes, the effects of these vaccines at the site of muscle injection and on the tumor microenvironment need to be more fully characterized." (PMID 41042672, 2025). "To further enhance the anti-tumor efficacy of Xcl1-E6E7, we explored the immunization of mice with the Xcl1-E6E7 plasmid in combination with several plasmids expressing interleukins known to stimulate T cell proliferation and memory formation, including IL-7, IL-9, IL-21, and IL-33." (PMID 39852828, 2025). "A tumor-colonized attenuated Salmonella typhimurium VNP20009 strain was engineered to synthesize granulocyte-macrophage colony-stimulating factor (GM-CSF) and interleukin 7 (IL-7), which helped recruiting macrophages and DCs and enhancing T cell antitumor responses." (PMID 40303342, 2025). "In this context, tumor cells with high IL-7R expression may co-opt IL-7 signaling to promote the enrichment of immunosuppressive TAM via CXCL1-dependent mechanisms; this process counteracts the potential immunostimulatory effects of IL-7." (PMID 41360767, 2025). "The combination of IL-12 and IL-7 enhanced the body’s immune response and activated an inflammatory state in previously less immunogenic tumors, contributing to complete regression of tumors and elimination of distant tumor deposits without toxicities." (PMID 38753073, 2024). "The C5/IL7-CAR-T did not provide significant tumor control at a dose of 2 million cells per mouse." (PMID 39450160, 2024). "IL-7 maintains CAR-T cells in a less differentiated T-cell state, regulates metabolic activities, and prevents CAR-T-cell depletion, which may be critical for CAR-T cells to maintain their metabolic adaptations and anti-tumor responses for up to several years." (PMID 39093440, 2024). "Similarly, CTSK can promote CRC progression by promoting M2 polarization of TAM through a TLR4-mTOR-dependent pathway, while M2 macrophages can secrete chemokines such as IL7 and EGFR to activate the NFκB pathway to further promote tumor tissue invasion and metastasis." (PMID 37930479, 2023). "Our previous studies indicated that gene modification to express IL‐7 and CCL19 in antitumor effector T cells, such as CAR‐T and TCR‐T cells, profoundly enhances therapeutic effects for solid cancers by inducing a massive infiltration of immune cells in tumor tissues and long‐term memory responses." (PMID 37031457, 2023). "Interestingly, the expression of Flt3L remained stable despite the introduction of antigen-negative tumor cells, while IL7 expression seemed to diminish as 2A cells were introduced, although not significant." (PMID 36817432, 2023). "However, FITC CAR T cells expanded in IL-7 and IL-15 rather than IL-2 did not demonstrate enhanced tumour control." (PMID 37291434, 2023). "A possible explanation for the lack of tumor regression is that IL-7 by itself does not induce potent effector functions in CD8+ T cells and would likely require a combination approach involving an immune-stimulatory factor to fully unlock its therapeutic potential." (PMID 38019919, 2023).